ENO2 (enolase 2)
Diseases named in the same sentence as ENO2 in open-access papers (continued):
Sharing a sentence is not in itself a finding about the gene and the disease.
cancer (continued). "Although not unidirectional, most of the observed differences (downregulation of proteins such as enolase 2, c-Met, mesothelin, PDGF-AA, eNOS, IL-6, and upregulation of CA125) suggested a negative impact of CDC-EVs on pathways associated with cancer." (PMID 29245929, 2017). "Also, when Eno2 is upregulated in several cancers without any treatment, it can be used as a biomarker of illness." (PMID 39861068, 2024). "Among these proteins, AXL receptor tyrosine kinase (AXL), carbonic anhydrase IX (CA9), enolase 2 (ENO2), human epidermal growth factor receptor (HER) 1, HER2, HER3, progranulin (PRGN), and platelet-derived growth factor-AA (PDGF-AA) are primarily involved in cancer cell proliferation." (PMID 35745691, 2022). "Concerning ENO2, literature reports indicated upregulation in cancer rather than downregulation, as it occurred in our mutant transfected cells, but additional studies are needed to find any specific correlation of this subunit of the enolase in CRC and KRAS/BRAF mutations." (PMID 19087308, 2008).
adenocarcinoma (41 papers, 1999 to 2025). A common cancer characterized by the presence of malignant glandular cells. "LNCaP-NK1R and 22Rv1-NK1R demonstrated significant expression of NE marker CgA and ENO2 as well as the NE-related gene while the level of adenocarcinoma marker AR and PSA reduced." (PMID 37385990, 2023). "Immunostaining of synaptophysin and qRT-PCR analysis of the NEPC-related genes (Syp, Chga, and Eno2) in the adenocarcinoma of different lobes also showed no significant changes in NEPC cell frequency or NEPC gene expression, respectively." (PMID 36369237, 2022).
infection (21 papers, 2004 to 2025). The state of being infected such as from the introduction of a foreign agent such as serum, vaccine, antigenic substance or organism. "In the same context as our findings, increased transcription of aldoa, pfk and eno2 has been observed in macrophages infected with L. major, 3 h post infection, supporting the activation of aerobic glycolysis in these cells." (PMID 35888991, 2022). "While SAG1 is already repressed 1d after infection, ENO2 and LDH1 were significantly repressed only after 4d of infection." (PMID 34610266, 2021). "Interestingly, unlike ldh1/ldh2 and eno1/eno2 which are expressed in a stage-dependent manner, both PGM isoforms (pgm1 and pgm2) were upregulated 6.4 and 3.1 folds, respectively, in the chronic stage, 28 days post-infection (dpi)." (PMID 35597992, 2022).
brain diseases (9 papers, 2010 to 2024). "Neuron-Specific Enolase (NSE) also known as enolase 2 or γ-enolase a dimeric isoform of the glycolytic enzyme enolase mainly found in neurons has been described as a biomarker for a number of brain disorders due to its elevation in cerebrospinal fluid and blood." (PMID 35255971, 2022).
ENO2 also shares sentences with these, for which no sentence is quoted: cardiac arrest (120 papers); Stroke (119); brain injury (57); squamous cell carcinoma (52); ischemic stroke (45); Sepsis (40); neurological disorders (32); injury (29); diabetes (25); small cell carcinoma (25); Cerebral ischemia (24); Cognitive impairment (24); delirium (24); Alzheimer disease (19); Encephalopathy (18); carcinoid tumor (17); COVID-19 (17); epilepsy (17); lymph node metastasis (17); neuroendocrine carcinoma (17); hypoxic-ischemic encephalopathy (16); lung adenocarcinoma (16); cerebral infarction (15); lymphoma (15); ischemia (14); neurodegenerative disease (14); dementia (12); depression (12); Hypertension (12); anemia (10).
A further 380 diseases each share a sentence with ENO2 in 9 papers or fewer.